FGF2 (fibroblast growth factor 2)
Diseases named in the same sentence as FGF2 in open-access papers (continued):
Sharing a sentence is not in itself a finding about the gene and the disease.
tumor (continued). "The present study shows for the first time that the FDA-approved antiviral agent CDV inhibits lung metastasis of virus-independent FGF2-driven tumor cells." (PMID 25609197, 2015). "FGF2 is a marker of cell proliferation during tumor development; moreover, the dramatic effects of FGF2 in cancer result from FGF2-induced shifts in gene expression." (PMID 26512645, 2015). "M1 macrophages are pro-inflammatory in function, they secrete IFN-γ, IL-12 and TNF-α, and therefore effectively suppress tumor growth while M2 like TAMs secrete TGF-β, IL-10, IL-17, IL-23, VEGF, and FGF2, promote angiogenesis and tumor progression." (PMID 26198107, 2015). "Hypoxia levels were reduced in tumor cells, resulting in decreased levels of metastasis-promoting genes (MMPs, VEGFs, FGF2, and CEBPD) thus impairing metastasis." (PMID 26010068, 2015). "Tissue injury leads to FGF-2 activation and subsequent promotion of wound healing processes known to promote tumor growth, invasion and angiogenesis." (PMID 26498838, 2015). "The soluble pattern recognition receptor long pentraxin-3 (PTX3) binds various FGFs, including FGF2 and FGF8b, thus inhibiting the angiogenic and tumorigenic activity of androgen-regulated tumor cells." (PMID 25912421, 2015). "We found that the combination treatment significantly decreased cancer cell invasion stimulated by FGF2 in vitro and tumor growth in vivo." (PMID 26575424, 2015). "The expression of FGF-2 was cytoplasmic in basal and parabasal layers with lining squamous epithelium, tumor cells and also in the tumor stroma." (PMID 26465941, 2015). "In this study the authors identify in the tumour microenvironment, fibrocyte-like cells derived from the bone marrow that mediate the resistance to bevacizumab through the production of FGF2." (PMID 26635184, 2015). "Studies have reported FGF-2 overexpression in high grade malignant tumours and malignant transformation of normal cells transfected with FGF-2 gene." (PMID 26465941, 2015). "In previous studies we have found that a Fibroblast Growth Factor Binding Protein (FGFBP1 or BP1), which was first identified in a tumor cell line, is a carrier molecule for FGF-2." (PMID 25429350, 2014). "In cancer, several oncogenes and tumour promoters are translationally controlled by hnRNPA1, including cMYC, Cyclin D1, FGF-2, XIAP and BCL-XL (this report), all of which possess IRESs in their mRNAs." (PMID 25324306, 2014). "Egr-1, first discovered as a gene rapidly induced in response to serum, has been shown to regulate FGF2 levels during angiogenesis and tumour growth." (PMID 24651658, 2014). "This further emphasises the possible role of nuclear FGFR1 and FGF2 in driving PDAC tumour invasion." (PMID 24503018, 2014). "At the transcriptional level, ablation increased Sele, Fgf2, Lifr and Cxcl12 in marrow and decreased Lifr and Sele in the surviving tumor." (PMID 24270800, 2014). "Examination of PDAC sections revealed that a significant percentage of myofibroblasts at the invading tumour front had nuclear FGFR1 and FGF2, compared to myofibroblasts in the central core of the tumour." (PMID 24503018, 2014). "These cancer and stromal cells secrete vascular endothelial growth factor (VEGF), fibroblast growth factor 2 (FGF2), tumor necrosis factor-α (TNF-α), and IL-6 into the surrounding area and these factors contribute to tumor-associated angiogenesis." (PMID 25502753, 2014). "As VEGF-A and FGF2 are important angiogenic factors, miR-503 can suppress tumour growth by inhibiting angiogenesis." (PMID 24944699, 2014). "3′ UTR shortening is, e.g., seen for fibroblast growth factor 2 (FGF-2), which is involved in tumor neovascularization." (PMID 23658553, 2013). "Our results also revealed that a large number of CD68+ tumor-associated macrophages were present in the tumor microenvironment of poor outcome tissue samples in which the CD30+ cells overexpressed both SDC1 and FGF2." (PMID 23988031, 2013).
tumor (continued). "FGF2 strongly inhibited the population growth and colony formation of Y1 and 3T3Ras tumor cells (compare FCS and +FGF2 conditions)." (PMID 23991123, 2013). "Several evidences show that SULFs are negative regulators of tumor cell growth, and that overexpression of SULFs in tumor cells inhibits cell growth by deregulating several factors, including FGF-2, HB-EGF and HGF." (PMID 24124496, 2013). "FGF-2 signaling that contributes to cell migration has been proven to be important in tumor progression and metastasis." (PMID 23468877, 2013). "During tumor angiogenesis, angiogenic factors (e.g., vascular endothelial cell growth factor (VEGF), fibroblast growth factor-2 (FGF-2), angiogenin, or angiopoietins) and their receptors are produced by tumor cells and endothelial cells (ECs)." (PMID 24180549, 2013). "The fibroblast growth factors FGF-1 and FGF-2 are heparan sulfate (HS)-binding proteins that play key roles in tumor angiogenesis, a critically important process in tumor growth and development." (PMID 22895025, 2012). "Secreted FGF2 can be released by several cell types around a tumour, mainly from the stroma and vasculature." (PMID 22732006, 2012). "Basic fibroblast growth factor (bFGF or FGF2) was the first angiogenic factor to be identified from a tumor extract, but vascular endothelial growth factor/vascular permeability factor (VEGF/VPF) is the best studied." (PMID 21977033, 2012). "One way this occurs is through tumor cell secretion of soluble factors, such as IL-1, FGF-2, PDGF, and/or TGF- β, which induce hepatocyte growth factor (HGF) secretion from fibroblasts." (PMID 22438903, 2012). "The expression and translation of FGF2 and NUDT6 are tightly linked, and show reciprocal patterns of expression in a variety of tissues during development, and in normal vs. tumor cells." (PMID 24704982, 2012). "Downregulation of the survival factor NF-κB and the angiogenic factors VEGF and FGF2 and increase in caspase-3 activity controlled tumor growth." (PMID 21822457, 2011). "Fibroblast growth factor receptor-1 (FGFR-1, CD331) is a high affinity receptor for basic fibroblast growth factor (bFGF, FGF2) and the signal transduction pathway induced by the bFGF/FGFR-1 interaction has an important role in stimulating tumor angiogenesis." (PMID 21385454, 2011). "We next investigated the effects of selective growth factors involved in vessel formation and maturation such as VEGF-A, PDGF-BB, FGF-2, TGFβ1 and conditioned media of tumor cells (A549 and PC3) on proliferation and differentiation of VW-MPSCs." (PMID 21637782, 2011). "Despite the high baseline invasion capacity of VW-MPSCs the application of both tumor cell supernatant and FGF-2 additionally increased their invasion capacity." (PMID 21637782, 2011). "FGF-BP has been shown previously to exert its tumor-promoting role through the activation of FGF2, and to activate FGF2." (PMID 22111880, 2011). "Silencing JAK1, JAK2 or TYK2 using RNA interference (RNAi) inhibits FGF2-mediated proliferation and results in the sensitization of tumor cells to chemotherapy-induced killing." (PMID 21625473, 2011). "We further show that the stem-cell culture cytokines EGF plus FGF-2 activate DNA repair and thus confound in vitro comparisons of DNA damage repair between stem-like and more differentiated tumor cells." (PMID 21663643, 2011). "M402 is a rationally engineered, non-cytotoxic heparan sulfate (HS) mimetic, designed to inhibit multiple factors implicated in tumor-host cell interactions, including VEGF, FGF2, SDF-1α, P-selectin, and heparanase." (PMID 21698156, 2011). "Fibroblast growth factor (FGF)-2 signaling induces the assembly of a multi-protein complex that provides tumor cells with the molecular machinery necessary for drug resistance." (PMID 21625473, 2011). "In vivo, the exogenous inoculation of FGF-2 mimicked the effect of hormones inducing HD tumor growth." (PMID 20553594, 2010).
tumor (continued). "The amount of FGF2-targeted adenovirus delivery to the liver was shown as a 10- to 20-fold decrease, whereas an increase of transgene expression in the tumour tissue was observed after systemic administration." (PMID 21063405, 2010). "The benefit of FGF2-targeted adenoviral system in tumour suppression was investigated using the MTT assay." (PMID 21063405, 2010). "Accordingly, tumor allografts in knockout mice for growth factors such as FGF-2 and MMPs such as MMP-2 and MMP-9 exhibit significantly reduced tumor growth and tumor-induced angiogenesis." (PMID 20804551, 2010). "For example, fibroblast growth factor-2 secreted by the tumor cells and tryptase secreted by host mast cells have been reported to act together to promote angiogenesis." (PMID 24281111, 2010). "Adenoviral-NBS1/Regular cisplatin and FGF2-Ad-NBS1/Reduced cisplatin had the greatest efficacy in shrinking tumour size and the effects were similar in both treatments." (PMID 21063405, 2010). "We demonstrated previously that CAF from HI tumors (CAF-HI) express high levels of FGF-2 and that FGF-2 induced HD tumor growth in vivo." (PMID 20553594, 2010). "For instance FGF-2 is frequently highly expressed in highly vascularized and advanced cancers and it has been reported that a synergistic action of FGF-2 and platelet derived growth factor-BB promotes tumour angiogenesis and pulmonary metastasis in mice." (PMID 20011604, 2009). "Fibstatin is a fibronectin fragment that binds FGF2 and inhibits FGF2-dependent proliferation, migration and tubulogenesis of ECs in vitro and angiogenesis and tumor growth in vivo." (PMID 22454596, 2009). "On the other hand, several lines of evidence indicate that FGFs, in particular FGF-2, play a key role in tumour angiogenesis." (PMID 20011604, 2009). "We have recently demonstrated that overexpression of GFG suppresses FGF-2 and inhibits cell proliferation in rat and human tumor cell lines." (PMID 18215310, 2008). "These factors, including TNF-α, IL-1α, IL-1β, VEGF, and fibroblast growth factor 2 (FGF-2), raise leptin levels and promote tumor growth and differentiation." (PMID 19017403, 2008). "This positive contribution of a Sulf to Wnt-dependent tumor growth is in striking contrast to several reports in which the enforced expression of Sulfs antagonizes other signaling pathways (e.g. FGF-2, and HGF) in tumor cells and suppresses cell growth." (PMID 17460759, 2007). "A number of reports demonstrated that over-expression of Sulf-1 or Sulf-2 in tumor cell lines inhibited growth factor signaling in response to several factors, including FGF-2, HB-EGF, and HGF." (PMID 17460759, 2007). "High levels of FGF2 activity in tumour cells suggested a role in cell proliferation and tumour angiogenesis." (PMID 15685229, 2005). "Studies of tumour perfusion with injected 86RbCl at equivalent tumour volumes of about 1800 mm3 indicated that the percentage of cardiac output to FGF-2 treated tumours was 33% greater than in sham-injected control neoplasms." (PMID 8398700, 1993). "The present study was undertaken to better define the kinetics of changes in hypoxic percentages as a function of tumour volume and FGF-2 treatment." (PMID 8398700, 1993). "Additionally, they release pro-angiogenic factors, such as VEGF and fibroblast growth factor 2 (FGF2), that not only increase tumour vascularization but also promote metastasis by enhancing tumour cell movement and intravasation." (PMID 40385641, 2025). "FGF2 (basic fibroblast growth factor) is a mitogenic and pro-angiogenic factor that is often secreted by CAFs within the tumor stroma; it can promote tumor cell proliferation, invasion, and new blood vessel formation, thereby facilitating tumor growth and dissemination." (PMID 41155518, 2025). "Moreover, N-cadherin increases the sensitivity of tumor cells to fibroblast growth factor 2 (FGF-2), which further enhances the expression of matrix metalloproteinase 9 (MMP-9)." (PMID 41181711, 2025).
tumor (continued). "Fibroblast growth factor 2 (FGF2), a growth factor produced by carcinoma‐associated fibroblasts, is reported to be involved in the proliferation, migration and chemotherapy resistance of tumour cells." (PMID 40845073, 2025). "Moreover, the expression rate of FGF2 was positively correlated with tumor aggressiveness and vascular density." (PMID 40141406, 2025). "The total level of macrophages (CD68 + ) was similar in both FGF2 high and FGF2 low tumor sites." (PMID 40425576, 2025). "Recruitment and activation of quiescent tissue-resident fibroblasts into CAFs involves a variety of tumor-cell-derived activators and modulators, including TGFβ, fibroblast growth factor 2 (FGF-2), hepatocyte growth factor (HGF), PDGF, stromal-derived factor-1 (SDF-1) and signaling pathways." (PMID 40805183, 2025). "Leptin promotes endothelial tube formation and increases vascular permeability by synergising with VEGF and fibroblast growth factor 2 (FGF-2), thereby facilitating tumour vascularisation and the establishment of a permissive vascular–stromal interface for cellular invasion." (PMID 41586225, 2025). "However, tumor tissue from the patients who underwent GTR secreted higher levels of FGF-2 (P < 0.001), as well as ENA-78, MCP-3, and IL-21 (all, P < 0.05)." (PMID 39923035, 2025). "To investigate this, we performed ELISA analysis for the primary pro-angiogenic substrates for each of these receptors (VEGFA, PDGF-BB and FGF-2), in tumour-conditioned media, with growth factor production from HFF1 cells also assessed by way of non-tumourigenic reference." (PMID 40469193, 2025). "We next investigated whether FGF2, produced by the tumor cells in the soft matrix PDEC cultures, was able to contribute to the macrophage polarization from M1 to immunosuppressive M2 type." (PMID 40425576, 2025). "High OS levels may also promote an increase in tumor-related fibroblast numbers via a growth factor present in the tumor microenvironment, possibly fibroblast growth factor 2 or tumor growth factor β." (PMID 40989158, 2025). "Via intercellular communication, tumor and tumor-associated stromal cells secrete various soluble pro-angiogenic proteins, importantly VEGF, FGF2, and PDGF that activate the tyrosine kinase receptors on endothelial cells to further upregulate downstream angiogenesis pathways (Z.-L." (PMID 41279931, 2025). "Additionally, M2 macrophages secrete pro-angiogenic factors such as VEGF and FGF2, promoting tumor vascularization and metastatic dissemination." (PMID 40109347, 2025). "Functional assays showed that silencing FGF2 slowed down tumor growth and reduced invasion." (PMID 39497721, 2024). "However, simultaneous inhibition of VEGF-A and FGF-2 signaling results in the inhibition of tumor growth." (PMID 38473833, 2024). "Likewise, an antifibroblast growth factor 2 (FGF2) IgG mAb, named 3F12E7 mAb, has been used to generate a scFv antibody that selectively targets FGF2 in tumor extracts." (PMID 39156005, 2024). "Indeed, FGF2 was shown to promote tumor angiogenesis via the up-regulation of VEGFR and VEGF-A, whereas VEGF, in turn, up-regulates FGF expression." (PMID 39272961, 2024). "Our finding reveals for the first time that FGF2 might recruit immune cells and enhance the drug sensitivity to exert an anti-tumor effect in BC." (PMID 38189813, 2024). "Elevated levels of FGF2 have also been detected in plasma samples from TNBC patients and patients with other tumours, indicating that FGF2 may be an important tumour-associated factor." (PMID 40135140, 2024). "In agreement, genetic knockdown of FGF-2 in NPC tumor cells could enhance the sensitivity of tumor cells to anti-angiogenic drugs." (PMID 38254110, 2024). "Notably, FGF1 and FGF2 are expressed in the presence of chronic disease in the liver, and their elevated expression levels correlate with more advanced tumor stages." (PMID 38473265, 2024).
tumor (continued). "In addition, as a crucial immunity regulator in the tumor micro environment, FGF2 affects macrophage programming and can alter macrophage polarization, tumor immunity and growth." (PMID 37919618, 2024). "We documented up-regulation in the expression of IFN-γ, IL12p70, IL-18, IL-20, MIF, TNF-α, TSLP, BLC, Eotaxin-1, Eotaxin-2, IP-10, MIP-1a, MIP-3a, FGF-2, MMP-1, TNFRII and TWEAK, which are implicated in the modulation of inflammation, apoptosis, tumor growth, invasion, and angiogenesis." (PMID 38954024, 2024). "Furthermore, GABA enhances tumor neovascularization by upregulating the expression of FGF2 in macrophages." (PMID 38894865, 2024). "Additionally, TAMs, which play a crucial role within the tumor microenvironment, are known to express FGF2." (PMID 38962005, 2024). "Additionally, we had previously identified several lung-derived soluble proteins associated with cell adhesion, stemness/plasticity, migration, and neoplasia including fibroblast growth factor 2 (FGF2)." (PMID 38581619, 2024). "FGF2 has been found to alter macrophage polarization, impacting tumor immunity and growth." (PMID 38745238, 2024). "FGF2 is crucial for tumor angiogenesis and alternative angiogenic pathways during Bev therapy." (PMID 38619734, 2024). "Basic fibroblast growth factor (FGF2) is a cytokine with broad mitogenic and cell survival activities, playing a crucial role in various biological processes, such as embryonic development, cell growth, morphogenesis, tissue repair, tumor growth, and invasion." (PMID 38953221, 2024). "In summary, our findings unveil an intricate signaling network involving METTL3/FGF2/PI3K/AKT/mTOR in LUAD and provide valuable insights into the molecular mechanisms underlying tumor progression, thus holding significant implications for targeted therapy and advancing LUAD research." (PMID 39497721, 2024). "However, when combined with fractionated radiation, the anti-FGF2 antibody treatment significantly delayed tumor growth in vivo, resulting in improved long-term survival and a higher ratio of M1-TAMs compared to irradiation alone." (PMID 38962005, 2024). "For this reason, FGF-2 seems to be an excellent candidate for the diagnosis of early tumor stages." (PMID 38672507, 2024). "Rescue experiments, clone formation and CCK-8 assays, were conducted to ascertain whether MIMT1 promotes tumour proliferation through FGF2." (PMID 39091947, 2024). "Accumulating evidence has shown that FGF2 signaling plays important roles in tumor lymphangiogenesis and lymph node metastasis, and may serve as a promising therapeutic target for lymphatic metastatic cancer." (PMID 39119899, 2024). "Tumor growth and angiogenesis: CAFs derived from ASCs secrete various growth factors and cytokines, such as fibroblast growth factor 2 (FGF2), vascular endothelial growth factor (VEGF), and CCL2, which promote both tumor growth and the formation of new blood vessels." (PMID 39519109, 2024). "Notably, FGF-2 directly sparks the survival and proliferation of OSCC cells; these pro-tumor effects add to FGF-2 angiogenic activity." (PMID 39120324, 2024). "We identified FGF2 signalling as a possible mechanism through which mesothelial cells could be promoting tumour growth." (PMID 37691350, 2023). "Interestingly, HOXB7 is functionally involved in tumor cell growth promotion through the direct transactivation of FGF2, which is also part of our 28-gene signature." (PMID 37445737, 2023). "Growing evidence has shown that FGF2 is altered in tumor tissues." (PMID 37432067, 2023). "Grange and colleagues performed molecular characterization of microvesicles and identified specific mRNAs associated with tumor progression and metastasis, including VEGF, fibroblast growth factor-2 (FGF2), angiopoietin-1 (ANGPT1), ephrin-A3 (EFNA3), metalloproteinase (MMP)-2, and MMP9." (PMID 37762660, 2023).